MMP9 (matrix metallopeptidase 9)
Diseases named in the same sentence as MMP9 in open-access papers (continued):
Sharing a sentence is not in itself a finding about the gene and the disease.
chondrosarcoma (continued). "Some individual chondrosarcomas also exhibited elevated levels of MMP-1, MMP-7 and MMP-9 mRNAs." (PMID 29316907, 2018). "The 5-year survival time for patients with chondrosarcoma with positive MMP-9 expression was 87%, compared to 36% in chondrosarcoma with negative MMP-9 staining." (PMID 29316907, 2018). "MMP-1, MMP-2, MMP-3, MMP-7, MMP-9 and MMP-13 are frequently expressed in chondrosarcoma tissues." (PMID 29361725, 2018). "Because fluid shear induces MMP-9 synthesis in human chondrocytes via PI3-K- and MAPK-dependent pathways, we evaluated the potential role of these signaling pathways in MMP-7 upregulation in shear-activated chondrosarcoma cells." (PMID 25823818, 2015). "The increase in MMP-13 expression may be necessary for the activation of other MMPs that have previously been identified in chondrosarcoma such as MMP-2 and MMP-9 it is also activated by MMP-2, MMP-3, and MTI-MMP." (PMID 18554405, 2008). "In consideration of semiquantitative scoring 64% of chondrosarcoma were scored as positive for MMP-1, 46% for MMP-3, 61% for MMP-9 and no for MMP-13." (PMID 29316907, 2018).
idiopathic pulmonary fibrosis (22 papers, 2005 to 2024). Idiopathic pulmonary fibrosis (IPF) is a nonneoplastic pulmonary disease that is characterized by the formation of scar tissue within the lungs in the absence of any known cause. "MMP-9 is over-expressed in alveolar macrophages in patients with idiopathic pulmonary fibrosis (IPF)." (PMID 23805173, 2013). "MMP-9, a type IV collagenase, is present at low levels in healthy lung tissue, but is elevated in idiopathic pulmonary fibrosis (IPF), COPD, and asthma." (PMID 26492278, 2015). "In lungs with usual interstitial pneumonia (UIP), MMP1, MMP2 and MMP9 are highly expressed." (PMID 28098218, 2017).
papillary thyroid cancer (22 papers, 2014 to 2024). "Compared to patients with benign multinodular goiter, those with papillary thyroid cancer (PTC) showed a significant increase (P = 0.004) in MMP9 levels." (PMID 37671970, 2023). "MMP9 and miR-145 expressions were analyzed in 175 paired papillary thyroid cancer (PTC) and normal tissues." (PMID 38001954, 2023). "Y. LI finds that by suppressing the expression of miR-155, sevoflurane inhibits the protein expression of MMP-2 and MMP-9, limits cell migration and invasion, and promotes cell apoptosis in papillary thyroid cancer cells." (PMID 37175113, 2023). "These consequences all prove that curcumin can be regarded as a high-efficiency and high-safety natural MMP-9 inhibitor, exhibiting great significance in the treatment of papillary thyroid cancer in many aspects." (PMID 37175113, 2023). "The aim of the present study was to investigate the association between matrix metalloproteinase-9 (MMP-9) expression with BRAF V600E mutation and clinicopathological features, in Iranian papillary thyroid cancer (PTC) patients." (PMID 30509240, 2018). "Curcumin inhibits the metastasis of K1 papillary thyroid cancer cells via down-regulating the expression of MMP-9 and up-regulating the expression of E-cadherin, which consequently suppresses the epithelial-mesenchymal transition (EMT) and reduces the viability and migration of tumor cells." (PMID 37175113, 2023). "In our previous work, we demonstrated that ouabain decreased cell migration and the expression of epithelial to mesenchymal transition (EMT) markers associated with tumor cell aggressiveness, such as vimentin, SNAIL-1 and MMP-9, in the human thyroid papillary cancer TPC-1 and BCPAP cell lines." (PMID 36551653, 2022). "In the current investigation, we aimed to evaluate the synergistic effects of celecoxib (CX) and sodium valproate (VPA) against cell survival, invasiveness properties, and expression of metalloproteinase-2 and -9 (MMP-2 and MMP-9) in papillary thyroid cancer cell line, B-CPAP cells." (PMID 30127823, 2018). "By regulating the miR-301a-3p/STAT3 axis, curcumin increases the expression of miR-301a-3p, decreases the expression of MMP-9 and EMT markers, and inhibits the viability, migration, and invasion of TPC-1 papillary thyroid cancer cells." (PMID 37175113, 2023). "Leptin and its derivative, OB3, both significantly reduce abundance of MMP9 mRNA in follicular thyroid cancer cells, but do not affect expression of MMP9 in papillary thyroid carcinoma cells." (PMID 32645835, 2020). "Furthermore, a reduction in the expression and activity of MMP-2 and MMP-9 could be possible by applying a non-atmospheric plasma on thyroid papillary cancer cells." (PMID 33799923, 2021).
pulmonary hypertension (22 papers, 2006 to 2025). Increased pressure within the pulmonary circulation due to lung or heart disorder. "In the SuHx animal model, which exhibits a more severe form of pulmonary hypertension, there is an activation of MMP9-mediated cleavage of COMP and subsequently loss of its stabilization of BMPR2." (PMID 38001814, 2023). "In our study, SSE decreased expression of MMP2 and MMP9 in the carotid artery in the balloon injury model, as well as the lung in the pulmonary arterial hypertension model." (PMID 33790787, 2021). "For example, MMP-9 expression is upregulated in human plexiform pulmonary arterial lesions and in lungs isolated from rats with monocrotaline-induced pulmonary hypertension." (PMID 30131961, 2018). "A study using a hypoxia-induced pulmonary hypertension model in Sprague-Dawley rats showed that the enhanced expression of MMP-9 disturbed this balance and led to pulmonary remodeling." (PMID 27688788, 2016). "In agreement with this suggestion, we and others have shown evidence implicating MMP-9 in APT-induced pulmonary hypertension and cardiomyocyte injury 14–38." (PMID 24199964, 2013). "A previous study showed that cilostazol therapy markedly suppressed the expressions of the TNF-α and MMP-9, two indicators of inflammation, in lung parenchyma of pulmonary arterial hypertension rats." (PMID 22897925, 2012). "In the lung tissue of rats with pulmonary hypertension, Mmp9 expression is upregulated." (PMID 40326772, 2025). "Furthermore, transgenic overexpression of human MMP-9 exacerbated monocrotaline-induced pulmonary hypertension in mice." (PMID 30131961, 2018). "By downregulating vascular endothelial cell adhesion molecule-1 and matrix metalloproteinase-9 (MMP-9) and upregulating PKG and endothelial nitric oxide synthase (eNOS), FGE decreased blood pressure in rats with pulmonary hypertension induced by monocrotaline." (PMID 38915405, 2024). "Baicalin clearly ameliorates pulmonary hypertension, pulmonary arterial remolding, and hypoxic cor pulmonale induced by hypoxia by inhibiting the p38 MAPK signaling pathway and MMP-9 expression." (PMID 27688788, 2016). "Morin and his colleagues discovered that, in a monocrotaline-induced pulmonary hypertension model, pulmonary artery remodeling might be improved via downregulation of the activity of p38 MAPK and the expression of MMP-9." (PMID 27688788, 2016). "Based on the role of MMP-9 in pulmonary arteriole remodeling, as confirmed by the literature, we concluded that the upregulation of MMP-9 mRNA and protein might also be involved in hypoxia-induced pulmonary hypertension." (PMID 27688788, 2016).
Sjögren’s syndrome (22 papers, 2005 to 2025). "Altered levels of proteins such as lactoferrin, lipocalin-1, and MMP-9 have been reported in ocular cicatricial pemphigoid, thyroid-associated orbitopathy, and Sjögren’s syndrome, correlating with inflammation severity." (PMID 41373875, 2025). "MMP-9 has been associated with chronic inflammatory autoimmune diseases, including rheumatoid arthritis, Sjögren's syndrome, idiopathic uveitis, and systemic lupus erythematosus." (PMID 15642145, 2005). "In particular, moderate to severe forms of aqueous tear-deficient DE conditions, such as Sjögren syndrome, could be underdiagnosed by the commercially available tear MMP-9 immunoassay." (PMID 32649686, 2020). "Other ocular surface pathologies in which MMP-9 activity is elevated include diseases like Sjogren’s syndrome and blepharitis." (PMID 39464763, 2024). "Although the level was increased in both types compared with control, those with Sjögren’s syndrome showed a more prominent elevation of MMP-9 than those with meibomian gland dysfunction." (PMID 37354028, 2023). "Primary Sjögren’s syndrome (pSS) patients exhibit enhanced degradation of the salivary epithelium initially through MMP9 overexpression." (PMID 36008454, 2022). "The increase in MMP-9/TIMP-1 in Sjögren’s syndrome patients’ saliva is strongly involved in destruction of glandular and salivary duct tissues." (PMID 34437596, 2021). "Therefore, increased activity of MMP9 and other proteases reflects both the damage to the salivary gland structure and the active inflammatory processes characteristic of Sjögren’s syndrome." (PMID 41301757, 2025). "Furthermore, interleukin levels such as IL-1a, IL-1b, IL-6, IL-8, TNF-a, and MMP-9 have been detected in Sjogren’s syndrome patients." (PMID 39408709, 2024). "Molecular profiling of tears has revealed elevated levels of IL-6, IL-17, TNF-α, and matrix metalloproteinase-9 (MMP-9) in patients with OCP, TAO, and Sjögren’s syndrome, correlating with disease severity." (PMID 41373875, 2025). "Tear proteomics has already identified cytokines and proteases—including IL-17, IL-6, TNF-α, and MMP-9—that correlate with disease severity in OCP, TAO, and Sjögren’s syndrome." (PMID 41373875, 2025). "Garreto and colleagues also revealed a significant increase in the levels of Matrix Metalloproteinase-9 (MMP9), Neutrophil Elastase (ELANE), Cathepsin G (CTSG), and Myeloblastin (PRTN3) in the saliva of patients with Sjögren’s syndrome compared to healthy controls." (PMID 41301757, 2025). "MMP-9 and tear osmolarity could be elevated in patients with inflammatory types of DED, such as Sjögren syndrome or graft versus host disease DED." (PMID 39329649, 2024). "As an extreme example, we found that when the MMP-9 in-situ test and tear osmolarity measurements were performed for patients with Sjögren syndrome, the tear osmolarity was significantly higher (due to the reduced tear volume), and the MMP-9 test result was likely to be completely negative." (PMID 32934302, 2020). "In addition, expression of several genes known to be dysregulated in Sjögren's syndrome: CTSS, MHC-II, MMP9, Rab proteins (Rab3D, Rab27A, and Rab27B), IL12α, IFN-γ, TNF-α, and aquaporin 5 (Aq5), and the cholinergic muscarinic M3 receptor (M3R) were quantitatively measured using qPCR." (PMID 28348600, 2017). "Therefore, a highly inflamed ocular surface with decreased tear volume, such as that found in Sjögren syndrome, could show negative results because of the markedly decreased tear secretion, despite the highly elevated tear MMP-9 concentration." (PMID 32649686, 2020).
subarachnoid hemorrhage (22 papers, 2009 to 2025). A serious neurological disorder characterized by intracranial hemorrhage into the subarachnoid space. "Other authors describe the ability of astaxanthin to reduce the expression and activity of MMP-9 in the brain after experimental subarachnoid hemorrhage in rats." (PMID 39201397, 2024). "Nafamostat can also inhibit thrombin and MMP9 expression to protect brain injury at the early stage of subarachnoid hemorrhage." (PMID 35842640, 2022). "Recently, inhibition of toll-like receptor 4 (TLR4) was found to prevent the induction of increased BBB permeability and suppress the upregulation of MMP-9 after subarachnoid hemorrhage in mice." (PMID 33487119, 2021). "MMP9 is also involved in the pathogenesis of early brain injury of subarachnoid hemorrhage through degrading Laminin." (PMID 21541054, 2011). "Similarly, minocycline, an inhibitor of MMP-9, has been related to better cognitive outcomes after a subarachnoid hemorrhage or in hypertensive small vessel disease." (PMID 38431757, 2024). "Furthermore, after subarachnoid hemorrhage in mice, MMP-9 is upregulated in the brain and mediates BBB permeability in a toll-like receptor 4 (TLR4)-dependent manner." (PMID 33487119, 2021). "Thus, the direct comparison of MMP-9 expression in the present ischemic model with that seen in experimental subarachnoid haemorrhage (SAH) and after organ culture of isolated MCA segments revealed enhanced levels of MMP-9 mRNA at 6 and 24 hrs." (PMID 19497125, 2009). "Lastly, a comprehensive imaging assessment of BBB disruption assessing subarachnoid hemorrhage, gadolinium sulcal enhancement [hyperacute injury marker (HARM)], or microvascular permeability (K2) would have been a more direct measure of MMP-9 action and deserves further investigation." (PMID 32582006, 2020). "Post-treatment with curcumin in subarachnoid hemorrhage (SAH)-induced mice preserved the integrity of the BBB and improved brain function via down-regulation of matrix metallopeptidase 9 (MMP-9) and inhibition of microglia cells, as well as reducing water content in the brain." (PMID 31489882, 2019). "The complex roles of JNK1/2 for acute brain injury have been investigated in models of subarachnoid hemorrhage and transient focal cerebral ischemia: Inhibition of JNK1/2 protects against mitochondrial apoptosis, reduces MMP-9 levels, inhibits BBB disruption, and reduces edema formation." (PMID 23691142, 2013).
brain inflammation (21 papers, 2008 to 2024). "Thus, RNT may be a good candidate in the treatment of brain inflammation associated with BK and MMP-9 overexpression." (PMID 35054789, 2022). "It was also shown that galangin blocks thrombin-induced MMP-9 expression, thus being a candidate for the management of brain inflammatory diseases." (PMID 38203364, 2023). "The induction of inflammatory mediators, such as MMP-9, in brain cells during brain inflammation is a result of numerous stimuli." (PMID 38203454, 2023). "The MMP-9 can be upregulated in several brain injuries and participates in the pathogenesis of various CNS disorders, including brain inflammation and BBB damage." (PMID 35740292, 2022). "In brain inflammation, several stimuli can induce the expression of diverse inflammatory mediators, including MMP-9 by ROS-mediated activation of the NF-κB cascade in brain cells." (PMID 35740292, 2022). "Taken together, these results suggest key roles of PGE2 autocrine and STAT3 in the severity of brain inflammation through up-regulation of MMP-9 in brain astrocytes." (PMID 33228717, 2020). "AP-1 is a crucial component for MMP-9 induction and a candidate for the treatment of inflammatory brain diseases." (PMID 31185608, 2019). "Matrix metalloproteinase-9 (MMP-9) plays a crucial role in pathological processes of brain inflammation, injury, and neurodegeneration." (PMID 23176293, 2012). "The inflammatory mediators MMP-9, COX-2 and p-NF-κB are associated with brain inflammation." (PMID 36341547, 2023). "The PKCs are crucial for regulation of MMP-9 in brain inflammatory diseases." (PMID 32505192, 2020). "Thus, in alignment with a previous manipulated animal study, the NF-κB inhibition significantly attenuated cerebral MMP-9 activity in brain inflammation." (PMID 29849502, 2018). "Among matrix metalloproteinases (MMPs), MMP-9 has been observed in patients with brain inflammatory diseases and may contribute to the pathology of brain diseases." (PMID 22643046, 2012). "Therefore, the development of drugs targeting the expression of MMP-9 and its upstream signaling components may be beneficial for the management of inflammatory brain diseases." (PMID 31185608, 2019). "Therefore, the inhibition of MMP-9-mediated inflammatory pathways may provide therapeutic strategies to brain inflammation and neurodegenerative diseases." (PMID 24455696, 2013). "Moreover, matrix metalloproteinases (MMPs), MMP-9 especially, have been observed in patients with brain inflammatory diseases and may contribute to brain disease pathology." (PMID 21092323, 2010). "Upregulation of HO-1 attenuates IL-1β-induced cell migration via inhibition of MMP-9 expression in RBA-1 cells and is therefore a potential strategy for treatment of inflammatory brain diseases." (PMID 29209167, 2017). "In a mouse model of meningitis induced by LPS, melatonin (5 mg/kg) significantly attenuated cerebral MMP-9 activity following brain inflammation; and in the RAW264.7 and BV2 cells, the results showed that pretreatment or cotreatment with melatonin effectively inhibited LPS-induced MMP-9 activation." (PMID 33808027, 2021). "However, the role of MMP-9 in astrocytes, the major regulator of fundamental biological functions of the CNS, in LTA-induced brain inflammation remains poorly defined." (PMID 22643046, 2012). "In brain injury, up-regulation of BK, ROS, and MMP-9 may increase BBB permeability, recruit immune cells infiltrating through BBB into the tissues, and subsequently result in brain inflammation and edema." (PMID 23176293, 2012). "ROS generation by IL-1β leads to the expression of several inflammatory genes like MMP-9 which may increase BBB permeability, recruit immune cells infiltrating through BBB into the tissues, and subsequently result in brain inflammation and edema during brain injury." (PMID 24455696, 2013).